IL17C (interleukin 17C)
Description:
Cytokine that plays a crucial role in innate immunity of the epithelium, including to intestinal bacterial pathogens, in an autocrine manner. Stimulates the production of antibacterial peptides and pro-inflammatory molecules for host defense by signaling through the NF-kappa-B and MAPK pathways. Acts synergically with IL22 in inducing the expression of antibacterial peptides, including S100A8, S100A9, REG3A and REG3G. Synergy is also observed with TNF and IL1B in inducing DEFB2 from keratinocytes. Depending on the type of insult, may have both protective and pathogenic properties, either by maintaining epithelial homeostasis after an inflammatory challenge or by promoting inflammatory phenotype. Enhanced IL17C/IL17RE signaling may also lead to greater susceptibility to autoimmune diseases.
Synonyms: IL-17C; CX2; IL-21; MGC126884; MGC138401
Tractability: Antibody: its Gene Ontology location is reachable by antibodies, with high confidence; UniProt places it where antibodies can reach, with medium confidence; UniProt predicts a signal peptide or a membrane-spanning region.
Gene: Protein-coding gene on chromosome 16 (88,638,572 to 88,640,468, forward strand). Ensembl gene ENSG00000124391.
Subcellular location: Secreted
Pathways (Reactome):
Immune System: Interleukin-17 signaling
Gene Ontology:
Molecular function: cytokine activity
Biological process: cell surface receptor signaling pathway; cell-cell signaling; inflammatory response; protein K63-linked ubiquitination; T-helper 17 type immune response
Cellular component: extracellular region; plasma membrane
Genetic constraint (gnomAD): Loss-of-function variants: 13 observed, 11.58 expected, observed/expected ratio (o/e) 1.12, 90% interval 0.73 to 1.73. The upper end of that interval is the gene's LOEUF score, 1.73, which puts it in group 6 of 6, group 1 being the genes least tolerant of losing a copy. Missense variants: 357 observed, 276.97 expected, observed/expected ratio (o/e) 1.29, 90% interval 1.18 to 1.41. Synonymous variants: 150 observed, 127.87 expected, observed/expected ratio (o/e) 1.17, 90% interval 1.03 to 1.34.
Homologues: Orthologues: chimpanzee IL17C (99% identical), macaque IL17C (94% identical), dog IL17C (78% identical), pig IL17C (75% identical), rat Il17c (73% identical), mouse Il17c (72% identical), guinea pig IL17C (70% identical), tropical clawed frog il17c (41% identical), Caenorhabditis elegans F25D1.3 (18% identical). Paralogues in human: IL17D (24% identical), IL17F (24% identical), IL17A (23% identical), IL17B (22% identical), IL25 (19% identical).
Diseases named in the same sentence as IL17C in open-access papers:
IL17C is named in the same sentence as 96 diseases in open-access papers, as found by Europe PMC text mining. Sharing a sentence is not in itself a finding about the gene and the disease. The quoted sentences say what the papers report.
psoriasis (62 papers, 2015 to 2026). An autoimmune condition characterized by red, well-delineated plaques with silvery scales that are usually on the extensor surfaces and scalp. "qPCR analysis showed that the psoriasis-associated genes IL17C, LL37, and IL36G (respectively) were induced upon stimulation with PMA NETs." (PMID 38783164, 2024). "IL-17C transgenic expression in keratinocytes induces psoriasis-like pathogenesis with thickening of the epithelium and production of pathogenic psoriasis cytokines." (PMID 32345660, 2020). "Within this family, IL-17A, IL-17C, and IL-17F are implicated in psoriasis pathogenesis as their expression is increased up to eightfold in psoriatic lesions." (PMID 30109481, 2018). "In addition, mRNA expression of the psoriasis-associated genes Il17a, Tnfa, S100a9, Il17c and Il1f9 was induced by tamoxifen in the ears and the back skin." (PMID 32597759, 2020). "Among others, important psoriasis-associated target genes of IκBζ include certain chemo- and cytokines (e.g., Cxcl1, Cxcl2, Cxcl5, Ccl3, and Il17c) as well as antimicrobial proteins, such as S100 calcium-binding proteins (e.g., S100a9), β-defensin-2 (Defb4), and lipocalin-2 (Lcn2)." (PMID 31622280, 2019). "Thus, the present study raises the possibility that future therapeutics for psoriasis could potentially target IL-17C selectively with a lesser risk of susceptibility to C. albicans." (PMID 25849644, 2015). "Elevated IL-17C expression has been reported in psoriasis, hidradenitis suppurativa and atopic dermatitis." (PMID 41488192, 2026). "Epithelial cells subsequently express IL-17C, with keratinocytes being the main producers in the context of psoriasis." (PMID 40536951, 2026). "Other cytokines from the IL-17 family—such as IL-17C, IL-17E, and IL-17F—are also believed to contribute to psoriasis development." (PMID 40536951, 2026). "For instance, IL-36 and IL-17C mainly act synergistically to enhance tissue inflammation; overexpression of IL-20 can lead to epidermal changes characteristic of psoriasis; and IL-19 potentiates the effects of IL-17A via a positive feedback mechanism." (PMID 40303401, 2025). "The IL-17 pathway-mediated immune cascade response plays a key role in the pathogenesis of psoriasis, e.g., lowering effector IL-17C expression reduces infiltrating immune cells and thus inhibits skin inflammation." (PMID 38542915, 2024). "In this review, we will summarize the current knowledge around IL-17A and its five currently known homologues, namely IL-17B, IL-17C, IL-17D, IL-17E (also known as IL-25) and IL-17F, in relation to skin inflammation in general and psoriasis in particular." (PMID 37283755, 2023). "Subsequently, we will summarize the current knowledge around IL-17A and its five currently known homologues, namely IL-17B, IL-17C, IL-17D, IL-17E (also known as IL-25) and IL-17F, in relation to psoriasis with a focus on the most recent discoveries." (PMID 37283755, 2023). "The expression of IL-17C was found to be increased in psoriatic skin and atopic eczema, representing a promising target for the treatment of psoriasis and atopic eczema." (PMID 38045694, 2023). "There are six known IL-17 family members including IL-17A, IL-17B, IL-17C, IL-17D, IL-17E, and IL-17F, with IL-17A and IL-17F being the best studied in psoriasis." (PMID 35008981, 2022). "Using MOR106, a specific anti-IL-17C antibody, it attenuated keratinocyte hyperproliferation and skin inflammation in mouse models of psoriasis and AD." (PMID 35075118, 2022). "As a result, in patients with moderate-to-severe psoriasis, we propose circulating IL-17C and PI3 as potential biomarkers of effective systemic anti-psoriatic treatment, and IL-17A as potential marker of CVD." (PMID 35008981, 2022). "IL-17C is the most abundant IL-17 isoform in lesional psoriasis skin, shares 27% homology with IL-17A and is produced by epithelial cells rather than hematopoietic cells that produce the other IL-17 family members." (PMID 35008981, 2022).
psoriasis (continued). "Brodalumab, a human monoclonal antibody against IL-17RA, which mediates the downstream signaling of IL-17A, IL-17F, IL-17A/F, IL-17C, and IL-17E, has been approved for the treatment of psoriasis." (PMID 35626662, 2022). "IL-17C is reported to be increased in keratinocytes in a number of inflammatory skin diseases, such as psoriasis and atopic dermatitis (AD)." (PMID 35075118, 2022). "IL-17C amplifies epithelial inflammation in human psoriasis and atopic eczema by potentiating the expression of other cytokines, chemokines, and HDPs as well as the autocrine induction of IL-17C in keratinocytes." (PMID 36359854, 2022). "In our wound-healing model, as well as in the models of experimental psoriasis and in lung cancer models, IL-17C mediates cell proliferation and growth." (PMID 34576717, 2021). "Extracts #8 and #13 downregulated IL-17C, a pro-inflammatory cytokine and a member of IL-17 family, that, together with IL-23 mediates inflammation in psoriasis, psoriatic arthritis, and ankylosing spondylitis." (PMID 33465050, 2021). "Given that IL-17C mediates keratinocyte proliferation and epidermal thickening in experimental models of psoriasis and atopic dermatitis, we wondered about the function(s) of the IL-17C/IL-17RE axis in the healing of wounds infected with S. aureus." (PMID 34576717, 2021). "Prior studies showed a detrimental role of IL-17C in the pathogenesis of immune-mediated skin diseases (e.g., psoriasis)." (PMID 34576717, 2021). "Different mouse models of psoriasis and atopic dermatitis demonstrated that IL-17C mediates skin inflammation, epidermal thickening, and keratinocyte proliferation." (PMID 34576717, 2021). "Transgenic mice lacking Il17c, Il17ra, or Il17re display a less severe course of imiquimod-induced psoriasis while an overexpression of Il17c in skin keratinocytes lead to spontaneous development of psoriasiform skin lesions." (PMID 32174926, 2020). "As significant efficacy of the anti-IL17C antibody has recently been noted in murine psoriasis and atopic dermatitis, its human use has been suggested." (PMID 32070069, 2020). "IL-17C also drives inflammation in atopic dermatitis as IL17C expression was increased in lesional skin of patients and blocking IL-17C with an antibody ameliorated skin inflammation in one mouse model for psoriasis and two models for atopic dermatitis." (PMID 32174926, 2020). "Psoriasis is associated with a pro‐inflammatory signature with elevated levels of tumour necrosis factor (TNF), IL‐17C and IL‐36 among other cytokines." (PMID 29744290, 2018). "IL-17C is a unique cytokine, a functionally separate member of the IL-17 family involved in inflammation enhancement in both psoriasis and AD." (PMID 30304837, 2018). "While these three cytokines act on keratinocytes to stimulate production of proinflammatory cytokines and chemokines, the exact role of IL-17C in psoriasis pathogenesis is poorly understood." (PMID 30109481, 2018). "The same neutralizing strategy led to an amelioration of the psoriasiform phenotype in IL-17C transgenic mice, pointing toward a possible role of the TNF/IL-17C axis in psoriasis." (PMID 30127781, 2018). "In the IL-23/Th17 axis model of psoriasis, IL-23 is able to produce and induce Th17 cell lymphocyte activation, which subsequently releases IL-17A, IL-17C, IL-17F, IL-22 and other related pro-inflammatory cytokines." (PMID 30544700, 2018). "Despite this evidence, IL-17C was shown to be upregulated in paradoxical psoriasis upon anti-TNF therapy in patients presenting inflammatory bowel disease (IBD), in a mechanisms depended on IL-36γ." (PMID 30127781, 2018). "In B6 mice, IMQ increased expression of Il17a, Il17b, Il17c, and Il17f, partially consistent with human psoriasis, but in the BALB/c strain such genes were unaltered by IMQ." (PMID 28279190, 2017).
psoriasis (continued). "A number of the SEs with the highest number of GRHL3 peaks overlap genes linked to psoriasis, like IL17C, providing further insight into the role of GRHL3 in psoriasis." (PMID 28445475, 2017). "Following the same line of thought, understanding the potential roles for the keratinocyte in the pathogenesis of psoriasis, we can take a look into the transgenic murine induction of IL-17C in the keratinocytes." (PMID 25973436, 2015). "Recently, we generated and reported a murine model of psoriasis driven by keratinocyte-specific overexpression of Interleukin (IL)-17C, the K5-IL-17C mouse." (PMID 26675482, 2015). "Notably, IL-17C is significantly elevated in the skin lesions of psoriasis patients and atopic dermatitis (AD) patients." (PMID 40536951, 2026). "Moreover, IL-17A principally drives the expression of four key cytokines: IL-36, IL-17C, IL-20, and IL-19, each possessing distinct functions in psoriasis." (PMID 40303401, 2025). "However, a differential role of IL-17B, IL-17C, IL-17D and IL-17E has been given during inflammation and, overall, in psoriasis." (PMID 40243580, 2025). "Research suggests IL-17C could be an effective biomarker for systemic anti-psoriasis therapy in moderate to severe psoriasis patients." (PMID 40303401, 2025). "Moreover, it notably decreased the expression of the genes encoding psoriasis-related cytokine and antimicrobial peptides, which were directly stimulated by the IL-17 pathway (e.g., PI3, DEFB4, IL17C, and TNFA)." (PMID 38951806, 2024). "An investigational IL-17C-specific antibody (MOR106) showed promising results in experimental studies for treatment of psoriasis and atopic dermatitis, however, phase II clinical trials for its use in atopic dermatitis were halted due to lack of efficacy (ClinicalTrials.gov Identifier NCT03568071)." (PMID 35008981, 2022). "The high affinity of brodalumab to human IL-17RA blocks the biological activities of the pro-inflammatory cytokines IL-17A, IL-17C, IL-17E, IL-17F, and IL17A/F heterodimer, resulting in inhibition of the inflammation and clinical symptoms associated with psoriasis." (PMID 36232430, 2022). "IL-17C shares several commonalities with IL-17A, in terms of immune and pro-inflammatory effects, and together with IL-17A forms a hypothetical “feed-forward” model contributing to keratinocyte hyperplasia and systemic inflammation in psoriasis." (PMID 35008981, 2022). "And keratinocyte-specific IL-17C transgenic mice developed a spontaneous psoriasis-like phenotype." (PMID 35075118, 2022). "Therefore, IL-17C is gaining interest as a candidate for therapeutic targeting in psoriasis and other autoimmune diseases." (PMID 35008981, 2022). "Thus, IL-17C/IL-17RE contributes to wound healing in infected wounds, but is detrimental in immune-mediated diseases, such as psoriasis." (PMID 34576717, 2021). "Considering that almost all IL-17 cytokines (notably IL-17A, IL-17F, IL-17C, and IL-17E) have been shown to play some role in psoriasis pathogenesis, an approach based on receptor blockade, rather than cytokine inhibition, provides a consistent and valuable treatment strategy." (PMID 34201664, 2021). "Apart from IL-17A, the other IL-17 family members (IL-17C, E, and F) may also be involved in the pathogenesis of psoriasis." (PMID 33281823, 2020). "The results indicate that IL-17C plays an important role in AD, apart from psoriasis." (PMID 30304837, 2018). "Finally, antibody-dependent blockade of IL-17C inhibited cutaneous inflammation in the IL-23-induced psoriasis model and in AD-like inflammation in mice." (PMID 30127781, 2018). "Indeed, a motif known to interact with TCF4 (5’-CAGGTG/CACCTG-3’) was more abundant in the 2 kb promoter region of the 191 IL17C-correlated genes as compared with all other genes expression in lesional skin of patients with psoriasis (PP) (P = 5.40 × 10–9, FDR = 1.47 × 10–6)." (PMID 38470486, 2024).
psoriasis (continued). "Therefore, it is tempting to speculate whether S. aureus contributes to the expression of IL-17C in psoriasis and atopic dermatitis and, thereby, to the IL-17C-mediated disease progression." (PMID 34576717, 2021). "Increased expression of IL-17C could also be detected in psoriasis and atopic dermatitis." (PMID 34576717, 2021). "IL-17C is a unique cytokine that is produced by keratinocytes and that is involved in such synergistic loops that may be responsible for amplifying the inflammation in both psoriasis and atopic dermatitis." (PMID 31649677, 2019). "Therefore, IL-17C neutralization may represent a novel therapeutic approach for sepsis, in addition to psoriasis and acute colitis." (PMID 30356086, 2018). "However, new evidence indicates that IL17C secreted by epithelial cells and keratinocytes may be a key driver of the psoriasis." (PMID 27050272, 2016). "Agents that inhibit IL-36, IL-17C, and JAK–STAT signaling are currently under investigation for moderate-to-severe psoriasis." (PMID 38348339, 2024). "CCL20, IL-6, IL-20, IL-17C, and PI3 were previously found to be elevated in patients with psoriasis." (PMID 39224116, 2024). "A number of serum analytes identified by Olink analysis, including PI3, IL-17C, CCL20, IL-20, IL-6, CXCL9, and CXCL10, have been previously identified as being elevated in serum samples of patients with psoriasis." (PMID 39224116, 2024). "It induces the expression of other psoriasis signature genes, such as IL36G, S100A15, DEFB4A, S100A9, CXCL8, TNIP3 (coding TNF-α-induced-protein 3 or TNFAIP3), and LCN2 (by synergy of IL-17C with TNF-α) in keratinocytes." (PMID 36928592, 2023). "The expression of IL-17C is increased by TNF-α in keratinocytes and has been suggested as a epithelial biomarker in the onset of skin-inflammatory diseases, including psoriasis and AD." (PMID 36012541, 2022). "We found that transcription levels of IL17A, IL17C, and IL17F were increased in psoriasis compared with normal skin, which was in parallel with their receptors IL17RA, IL17RC, IL17RD, and IL17RE." (PMID 36009523, 2022). "We further analyzed the correlation between the expression of these regulators and some well-known gene biomarkers of psoriasis (i.e. IL17A, IL17C, IL23A) and measures of disease severity (i.e. the PASI and PSI)." (PMID 35874668, 2022). "IL-17C and PI3 proteins are also interesting targets that merit further investigation in psoriasis treatment." (PMID 35008981, 2022). "In the present study, we found that CB2R KO contributed to the pathogenesis of psoriasis by promoting CD4+ T cell proliferation; upregulating Th17 cytokines, such as IL-17A, IL-23A, and IL-17C; and downregulating IL-10." (PMID 35173615, 2022). "Thus, antagonism of IL-17C may be beneficial for psoriasis and atopic dermatitis treatment." (PMID 31649677, 2019). "Bimekizumab treatment completely reversed the levels of cytokines/chemokines, anti‐microbial peptides, or proliferation‐related molecules, such as CXCL8, CCL20, IL‐17A, IL‐17F, IL‐17C, keratin 16, IL‐36γ, DEFB4, or S100A7, in psoriasis lesional skin to the levels of non‐lesional skin." (PMID 38482898, 2024). "It is noteworthy that IL-17C is not a specific target for psoriasis and AD but for a variety of inflammatory skin diseases." (PMID 35075118, 2022). "Along with IL-36α, IL-17C, and IκBζ, ROCK2 could be an equally important factor in the pathogenesis of psoriasis, which may involve self-sustaining circuits between innate and adaptive immune responses via regulation of IL-36α and IL-36γ expression." (PMID 35563374, 2022). "Interestingly, adaptive T-cell-derived cytokines IL17A, IL17F, IL17C, IL26, IFNG, IL4, and IL10 show comparable levels in skin biopsies from paradoxical and classical psoriasis." (PMID 29295985, 2018).
psoriasis (continued). "The loss of IL-17A/PASI correlation in the presence of atherosclerotic CVD, together with the decreased correlations of PI3, IL-17C, CCL20 and TGF-α with PASI in these patients, clearly merits further investigation and may contribute to further understanding of the links between psoriasis and CVD." (PMID 35008981, 2022). "Similarly, we show that also neutrophils isolated from patients with active psoriasis do not express IL-17F, IL-17B, IL-17C, IL-17D, and IL-17E as well as IL-17RC mRNA when activated by R848, IFNγ plus LPS, and IL-17A in vitro." (PMID 29719541, 2018). "However, the effects of IL17-C on the mechanisms of psoriasis are not clear." (PMID 33281823, 2020). "In psoriasis patients, IL17C mRNA is upregulated and expression of IL-17C increased compared to non-lesional or healthy skin; indeed, keratinocytes produce IL-17C in much higher amounts than IL-17A." (PMID 34201664, 2021).
atopic dermatitis (14 papers, 2018 to 2026). "Interleukin 17C (IL-17C) modulates epithelial inflammation and has a possible role in atopic dermatitis (AD) pathology." (PMID 36498818, 2022). "Therapeutic anti-IL-17C-antibodies which are currently developed for the treatment of atopic dermatitis could be implemented in clinical studies." (PMID 33411748, 2021). "Importantly, IL-17C is overexpressed in lesional skin of psoriatic and atopic dermatitis patients." (PMID 30127781, 2018).